C3 (complement C3)
Diseases named in the same sentence as C3 in open-access papers (continued):
Sharing a sentence is not in itself a finding about the gene and the disease.
infection (continued). "Using a 96-well dot blotting device a transient elevation of C3 secretion in urine was found in patients suffering from serious infection." (PMID 34767613, 2021). "Nevertheless, our knowledge about C3-dependent immune responses and its mode of action during infections by intracellular bacteria, e.g., Chlamydia, is still scarce." (PMID 33746963, 2021). "infection from the infected lung to dLN also depends on C3 and the C3a and C5a anaphylatoxin receptors." (PMID 33767691, 2021). "If an infection or exposure does occur, an immediate and most effective treatment should be followed to minimize the activation of the C3 system to avoid damage to his renal allograft." (PMID 34149444, 2021). "By day 35 post infection, there was a significant increase in survival of C3.1-treated mice (100% survival), compared to DPBS control mice (40% survival)." (PMID 34200478, 2021). "For Nm, addition of only 0.09 μg mL−1 fD resulted in a half maximal increase in complement C3 deposition, indicating that for this type of infection only very low fD levels are needed to offer protection." (PMID 33841879, 2021). "We strongly suggest that urinary C3 of critically ill patients suffering from serious infections is the result of synthesis and secretion from renal epithelial cells." (PMID 34767613, 2021). "Involvement of humoral immunity, and lung deposition of IgG, IgM, IgA, and C3, have been demonstrated in both experimental, and spontaneous infection." (PMID 33567544, 2021). "To evaluate the impact of the C3-cleaving phenotype on the resistance of P. aeruginosa to the complement-mediated phagocytic killing, we used an ex vivo model of infection, but using blood, that contains phagocytic cells, instead of serum." (PMID 35145924, 2021). "The potential role for intracellular C3 in self-defense against infection warrants further investigation." (PMID 34408631, 2021). "Hallmarks of cell death and inflammation, including cleaved caspase-1 and −3, gasdermin-D, neutrophil elastase, catalase, complement C3, and myeloperoxidase were validated in lung tissues on day 6 after infection via immunoblot." (PMID 34319784, 2021). "The anaphylatoxins C3a and C5a are small fragments, which result from the cleavage of C3 and C5 respectively—C3a and C5a promote migration of immune cells to sites of infection and thus have a critical role in the activation of immune cells." (PMID 33224139, 2020). "These patients had more often low serum C3 levels, a mixed histologic pattern in kidney biopsies and presented more frequently serious infections during follow-up." (PMID 32787590, 2020). "Two patients had C3 and/or C5 nephritic factors and 5 patients had infection-related complement consumption." (PMID 32972440, 2020). "We find that mutation of c3a.1 in larval zebrafish impairs neutrophil recruitment to localized bacterial infection and show a neutrophil-dependent role for C3 in survival in response to these infections." (PMID 32973200, 2020). "It has been reported that the levels of C3 and C4 in the serum of M. fortis are significantly higher than those in the serum of mice before infection and are increased in both hosts after infection with S. japonicum." (PMID 33013763, 2020). "Upon infection, hydrolysis of C3 into C3b occurs on the viral surface, which sequentially becomes inactivated into iC3b." (PMID 32876566, 2020). "We demonstrate a role for C3 in priming neutrophils for efficient migration to infection and wounds; however, the role of autocrine neutrophil C3 signaling warrants further investigation." (PMID 32973200, 2020). "The pro-inflammatory anaphylatoxins C3a and C5a, which are generated by cleavage of complement factors C3 and C5, support these anti-Candida effects by chemotactically attracting phagocytes to the site of infection." (PMID 32765510, 2020).
infection (continued). "Compared to WT mice, C3−/− mice exhibited significantly fewer yeast cells in the liver following infection, and most yeast cells were released back into the bloodstream following a transient stop." (PMID 31594939, 2019). "When the mice were C3-depleted using CVF before the infection, the survival of the CVF-treated mice was significantly decreased against E. coli K1 infection compared to the non-CVF-treated mice." (PMID 31295956, 2019). "The identification of CSF1R+ macrophages/monocytes as a local source of C3 during infection is also critical, as these cells are recruited to the cornea in the early stages of HSV-1 infection and are associated with corneal nerve damage in HSV-1 keratitis." (PMID 31414985, 2019). "Complement C3 is an essential immune regulator of host defence against infection, cell integrity, and tissue homeostasis in the peripheral system." (PMID 31637049, 2019). "Following infection three different complement activation pathways commence rapidly to activate complement component 3 (C3)." (PMID 30934602, 2019). "Among these receptors, CR1 and CR2 on monocytes are involved in phagocytosis via interactions with the C3 complement during infection." (PMID 31616424, 2019). "The reduced capture ability in the liver resulted in impaired blood clearance and an increased half-life of circulating yeast cells in C3−/− mice, which was confirmed by the enhanced blood CFU in C3−/− mice post infection." (PMID 31594939, 2019). "As for CBA/Ca, Cfb, a protein of the alternative pathway, is upregulated under infection when compared to its counterpart control, together with C8g, C3 and Cfh." (PMID 31412915, 2019). "In the absence of complement C3, subcutaneous injection of V3533 resulted in high viremia titers, an early appearance in the brain and spinal cord, and prolonged viremia compared to infection in the wild-type mouse with functional C3." (PMID 30781656, 2019). "Regarding the laboratory test results, the hemoglobin (11.1 ± 2.2/μL vs. 11.8 ± 1.7/μL, p = 0.001) and C3 (78.2 ± 40.2 mg/dL vs. 87.4 ± 39.5 mg/dL, p = 0.043) levels were lower in the infection group than in the control group." (PMID 31273256, 2019). "Our results show a similar expression level of CRP and C3 in both mice strains prior to infection, as well as during the following time points post-infection, suggesting a similar capacity to activate the classical complement pathway." (PMID 30333823, 2018). "We confirmed, in an independent set of experiments (n = 3), that indeed ΔLasB-PAO1 infection induced higher levels of C3 and that the downregulation with WT-PAO1 was proteolytically mediated since PA, the LasB inhibitor, partly reversed the phenotype." (PMID 30083156, 2018). "For the C3 gene, the DNA methylation level in the control group was slightly changed and ranged from 59.67 ± 2.02% to 65.00 ± 2.50% during the infection process." (PMID 29642440, 2018). "The C3 region of gp120 is under selection pressure during human infection with the BG505 virus, and we had found that this region influences neutralization by sera from BG505 trimer-immunized rabbits." (PMID 29474444, 2018). "Acknowledging that differences in the extent of bacterial uptake existed between the two opsonization conditions, we equalized initial uptake of the pathogen in HS and C3-depleted HS by adjusting the multiplicities of infection (MOI)." (PMID 29312899, 2017). "Depletion of C3 via CVF treatment delayed H5N1 and H1N1 influenza virus clearance in guinea pigs and was associated with increased lung damage during infection." (PMID 28418930, 2017). "Short-term inhibition of C3 would be of no concern, provided antibiotic prophylaxis, whereas long-term systemic inhibition would increase the risk of infection, as the main complement protection against infection is opsonization by C3 of microbes." (PMID 27581539, 2017).
infection (continued). "The difference in clearance of bacteria from the site of infection to the locally draining inguinal lymph node observed in both wildtype and C5 deficient mice was diminished in C3-/-/C5-/- mice, suggesting that cleavage of C3 may be responsible for this phenotype." (PMID 28806402, 2017). "It was demonstrated that in the acute phase of the disease, both infection-induced and aHUS patients trended toward decreased average C3 levels and increased average AP activity, even though this difference was not statistically significant in all groups." (PMID 27718086, 2017). "Similar to what has been reported in mice, infection of guinea pigs with H1N1 and H5N1 influenza viruses caused significant increases in serum C3 levels." (PMID 28418930, 2017). "To validate a clear role for the C3-ase activity of ScpA in vivo, utilizing the same soft-tissue infection model, we compared the pathogenesis of GAS-M1 and GAS-M1ΔscpA in complement deficient (C3-/-/C5-/-) mice." (PMID 28806402, 2017). "Based on the observed differential C3b deposition by NTHi375 WT and ΔthyA strains, we next tested the effect of C3 in NTHi infection of A549 cells." (PMID 28676846, 2017). "C3 is the central molecule of the complement cascade, and plays a vital role in opsonization of bacteria and recruitment of neutrophils to the site of infection." (PMID 28806402, 2017). "In the present study, we administered intracerebroventricularly lipopolysaccharide (LPS) to mimic local infection of the brain and investigated the role of key complement component C3 in brain vasculature endothelial activation and leukocyte recruitment." (PMID 26822321, 2016). "The relevance of complement activation for the immune response against C. albicans is demonstrated by infection of C3- and C5-knockout mice, which show increased mortality as a consequence of impaired anti-Candida response and infection-driven immunopathology." (PMID 28133459, 2016). "In the present study, we observed an increase in the gene expression for complement including C6, C4A, CR2, C3 at 8wks post infection." (PMID 27467147, 2016). "Compared with the non-infection group, the levels of C3 and C4 were significantly higher in the infection group (p <0.01)." (PMID 26497060, 2015). "C3 and C4 are the most commonly measured complement components and help the body’s immune system to react to both inflammation and infection." (PMID 26497060, 2015). "The results demonstrated that only the levels of C3 and C4 were lower in the infection group than in the non-infection group." (PMID 26497060, 2015). "At 24 hours after infection, a small but statistically significant increase in C3-fragment opsonization was found for insulin-rescued rats compared with diabetic rats (P = 0.05)." (PMID 25610878, 2014). "In order to evaluate the forms of C3 bound to S. aureus, we performed C3 Western blot analysis on bacteria recovered at 2 hours after infection." (PMID 25610878, 2014). "Levels of functional C3 or C4 assessed by hemolysis assay are reduced after infection by flaviviruses such as Dengue virus and West Nile virus (WNV)." (PMID 24349192, 2013). "In this regard, during infection of murine macrophages with Mycobacterium avium, C3-depletion results in a significantly higher level of TNFα production." (PMID 23359218, 2013). "Next, we investigated the cellular source of C3a and C5a and assessed the ability of lung mDCs to synthesize and secrete C3 and C5 during infection." (PMID 23326231, 2013). "The fact that 1 IL-1β and IL-8 are highly induced while C3 remains moderately expressed is consistent with the expected expression profile at the early stages of infection (3 days in our case)." (PMID 22429905, 2012). "In low-dose infection, viable chlamydiae were still detectable on day 21 in 4/8 (50%) spleens from C3−/− mice, again in the range of 105 IFU, whereas 8/8 WT mice tested negative." (PMID 23189195, 2012).
infection (continued). "Upon establishment of P. intermedia and P. gingivalis at the site of infection, higher concentrations of proteases lead to complement inhibition by degradation of C3, C4 and C5." (PMID 22514678, 2012). "This study demonstrates for the first time a strong and complex influence of complement effector functions, downstream of C3 and upstream of C5, on the outcome of an infection with intracellular bacteria, such as C. psittaci." (PMID 23189195, 2012). "In a model of polymicrobial infection, S. aureus in elevated glucose conditions depleted C3 from serum resulting in decreased complement-mediated killing of E. coli." (PMID 22390383, 2012). "Although C3 opsonization of pathogens including B. anthracis facilitates early infection steps, the pathogens inhibit the host complement attack and apparently utilize diverse escape mechanisms." (PMID 21464960, 2011). "Using a mouse-specific C3 sandwich ELISA we found that within 3 days post-infection (dpi) C3 levels were >3-fold higher in the H5N1 VN/1194 virus infected mice as compared to controls and continued to increase to >4-fold by 6 dpi." (PMID 21408070, 2011). "Such response was observed in our experimental model since it was observed presence of binding of antibodies, C3 and C9 components to trophozoites during all time points of infection." (PMID 20338063, 2010). "Positive diffuse reaction to C3 complement component was more intense in livers of animals inoculated with E. histolytica after 24 and 72 h of infection." (PMID 20338063, 2010). "Antibodies of the IgG2a/c and IgG2b subclass fix complement proteins C1q and C3 and can opsonize and inhibit infection." (PMID 20582312, 2010). "Overall, by altering two amino acids in the C3 region the virus in CAP88 escaped the anti-C3 antibodies that arose within the first 6 months of infection." (PMID 19763271, 2009). "This key mechanism is further confirmed by the fact that in infection-inflammation condition, the CRP∶L-ficolin amplification pathway caused more C3-deposition." (PMID 19180241, 2009). "Using this approach, serum from CAP88 was shown to contain at least 2 antibody specificities within the first year of infection targeting the C3 and the V1V2 regions." (PMID 19763271, 2009). "In contrast, less than half of the C3−/− mice survived to day 10, and of these, over 75% had ongoing infection of the spleen and liver (7 of 9, P = 0.008 and 0.01, respectively)." (PMID 19112490, 2008). "By day 7 post-infection, the C3−/− mice had 45-fold higher viral titers in the liver (P = 0.01), and there was also a similar trend in the spleen (6-fold, P = 0.09)." (PMID 19112490, 2008). "We compared C3−/− and wild-type mice for histopathological changes in the liver on days 4, 7, and 10 post-infection." (PMID 19112490, 2008). "Notably, intracellular C3 has been shown to activate NF-κB p65 to trigger cell-autonomous immunity during infection." (PMID 41044292, 2026). "To clearly identify the primary source of complement C3, we conducted an enzyme-linked immunosorbent assay (ELISA) using MACS-isolated microglia and astrocytes from the striatum of mice infected with S. aureus on day 3 post-infection." (PMID 40294039, 2025). "Additionally, we examined the function of C3 mutants in the context of TbCSV∆C3 infection, a mutant virus with untranslated C3 that was constructed and used in our previous report." (PMID 40025647, 2025). "Additionally, studies have demonstrated that recombinant C3 protein can mitigate post-infection inflammatory responses and histopathological damage, while enhancing the phagocytosis of Streptococcus agalactiae by monocytes and macrophages." (PMID 41463861, 2025). "The absence of C3 was associated with significantly higher leptospiral loads in the kidneys, liver, spleen, and urine compared to WT mice at 3 and 6 days post-infection (d.p.i.)." (PMID 41251377, 2025).
infection (continued). "In order to investigate the role of the complement C3-C3aR pathway in the S. aureus-induced infection, we employed the complete deletion of complement C3 and C3aR as well as constructed conditional astrocyte-specific C3 knockout mice (Aldh1l1Cre-ERT2; C3flox/flox)." (PMID 40294039, 2025). "The risk of infection increased with higher age and sALB levels, decreased with increasing eGFR and C3 levels, and showed a non-linear pattern with RTX—rising initially and then declining." (PMID 41209009, 2025). "The alternative pathway promotes the depletion of the C3 component as a mechanism that promotes a quick amplification of the pro-inflammatory responses; C3 products are reported to be involved in the opsonization of the parasites during infection." (PMID 40430767, 2025). "Second, the removal of C3-C3aR signaling alleviates astrocyte-microglia crosstalk is intriguing, but the impact of microglia-inherent variability influences the transcriptional response of S. aureus during in vivo infection is likely to be limited." (PMID 40294039, 2025). "Thus, we sought to investigate the role of C3 in resolving infection by C. burnetii NMII using the C3 knockout mouse model B6.129S4-C3tm1Crr/J (C3 KO)." (PMID 40586810, 2025). "The results showed that both LAMB1 and C3 were upregulated within 24 h of infection." (PMID 40237496, 2025). "We found that colocalization between microglia and C3 increased after infection." (PMID 40008883, 2025). "The increased complement C3 content in 2021 compared to 2020 may confirm the activation of the complement system in response to breakthrough infection with Omicron." (PMID 40284924, 2025). "Furthermore, the heatmap of the DEG list highlighted the significant upregulation of multiple genes related to the complement system on D1 and D7 post-infection, including complement C3, C3ar1, Itgax, Itgb2, and C1ra." (PMID 40294039, 2025). "As in the initial infection phase, transferred HIV virions are opsonized by complement proteins (i.e.C1q or C3), enhancing viral uptake, we compared the infection potency and distribution of complement-opsonized HIV (HIV-C) and non-opsonized HIV-1 (HIV-1) in FCS- and hPL DCs." (PMID 41041316, 2025). "Moreover, the immunostaining also revealed an upregulation of complement C3 and C1q levels in the striatum post-infection by S. aureus, corroborating the complement activation in both the acute phase and later stages of S. aureus infection." (PMID 40294039, 2025). "This suggests that during the infection process, C3 genes will be continuously triggered and coordinate intricate defense mechanism in cotton, such as oxidative burst, synthesis of antimicrobial compounds, and hormone signaling, to effectively block further invasion and spread of the pathogen." (PMID 40791784, 2025). "P62 gradually reduced with the duration of infection, and C3+ive-S." (PMID 39310788, 2024). "These experiments showed that the normally high bacterial burden in tissues of infected C3–/– mice were reduced in C3 NIMA mice, demonstrating that being born to complement-sufficient mothers can dominantly affect infection susceptibility of otherwise genetically identical complement-deficient mice." (PMID 39541162, 2024). "In its activated form, C3 facilitates the opsonization of particles and pathogens, which enhances the recognition and phagocytosis of these particles by macrophages within the kidney, preventing the spread of infection and maintaining tissue integrity." (PMID 38921822, 2024). "In mice, lack of C3 complement impairs progression of skin lesions caused by L. major, decreasing the presence of neutrophils during infection." (PMID 39028711, 2024). "Second, regulation of C3 and FB synthesis during viral activation of complement is shown to have a potentially profound effect on how the AP responds to infection, since this appears relevant to observational evidence that AP dysregulation is associated with clinical outcomes in COVID-19 infections." (PMID 38234438, 2024).